COXFA4L3 (cytochrome c oxidase associated subunit FA4L3)
Description:
Mitochondrial small peptide that orchestrates a two-pronged immunoregulatory mechanism in response to inflammatory stimuli. Replaces the canonical cytochrome c oxidase subunit COXFA4 in mitochondrial complex IV and targets it to degradation, attenuating mitochondrial respiration, reducing membrane potential as well as ROS generation and modulates innate immune signaling. Additionally, initiates stress-independent autophagy by lowering ATP levels, activating AMPK-ULK1 signaling, boosting glutathione production, and thereby mitigating oxidative stress and supporting immune tolerance.
Synonyms: MOCCI; NMES1; C15orf48; MIR147BHG; MISTRAV; FOAP-11
Tractability: No criterion of Open Targets' tractability assessment is met for any kind of drug.
Gene: Protein-coding gene on chromosome 15 (45,430,579 to 45,448,761, forward strand). Ensembl gene ENSG00000166920.
Subcellular location: Mitochondrion inner membrane
Gene Ontology:
Molecular function: protein binding
Cellular component: mitochondrion; nucleus; mitochondrial inner membrane
Genetic constraint (gnomAD): Loss-of-function variants: 11 observed, 13.45 expected, observed/expected ratio (o/e) 0.82, 90% interval 0.51 to 1.35. The upper end of that interval is the gene's LOEUF score, 1.35, which puts it in group 5 of 6, group 1 being the genes least tolerant of losing a copy. Missense variants: 79 observed, 101.72 expected, observed/expected ratio (o/e) 0.78, 90% interval 0.65 to 0.94. Synonymous variants: 28 observed, 33.03 expected, observed/expected ratio (o/e) 0.85, 90% interval 0.63 to 1.16.
Homologues: Orthologues: macaque C15orf48 (92% identical), dog C30H15orf48 (83% identical), pig C15orf48 (81% identical), chimpanzee C15H15orf48 (77% identical), guinea pig C15orf48 (77% identical), mouse AA467197 (72% identical), rat C3h15orf48 (71% identical), zebrafish C18H15orf48 (58% identical). Paralogues in human: COXFA4 (30% identical), COXFA4L2 (24% identical).
Diseases named in the same sentence as COXFA4L3 in open-access papers:
COXFA4L3 is named in the same sentence as 45 diseases in open-access papers, as found by Europe PMC text mining. Sharing a sentence is not in itself a finding about the gene and the disease.
COXFA4L3 shares sentences with these, for which no sentence is quoted: tumor (12 papers); cancer (9); COVID-19 (6); infection (5); esophageal squamous cell carcinoma (4); lung carcinoma (4); rheumatoid arthritis (4); squamous cell carcinoma (3); breast carcinoma (2); cervical cancer (2); esophageal cancer (2); glioma (2); lung adenocarcinoma (2); pancreatic cancer (2); viral infection (2); acute myeloid leukemia (1); adenoid cystic carcinoma (1); adenoma (1); atherosclerosis (1); autoimmune disease (1); Autoimmunity (1); cardiovascular diseases (1); clear cell Renal Cell Carcinoma (1); colon cancer (1); colorectal cancer (1); endothelial dysfunction (1); gastric cancer (1); gastrointestinal disease (1); gastrointestinal disorders (1); glioblastoma (1).
A further 15 diseases each share a sentence with COXFA4L3 in 1 paper.